IL17B (interleukin 17B)
Diseases named in the same sentence as IL17B in open-access papers (continued):
Sharing a sentence is not in itself a finding about the gene and the disease.
tumor (continued). "Thus, we treated the cells with recombinant IL-17B (rIL-17B) to directly stimulate IL-17RB signaling in tumor cells." (PMID 33649532, 2021). "Our study demonstrates the tumor-promoting effect of PSCs via IL-17B/IL-17RB signaling." (PMID 34771503, 2021). "IL-17B acts as tumor promoter in several solid and hematopoietic malignancies." (PMID 33244315, 2020). "Importantly, in each study, inhibition of the IL-17B/IL-17RB axis by downregulating receptor expression in tumor cells or by using neutralizing anti-IL-17RB antibodies restored chemosensitivity in vitro and in vivo." (PMID 32373132, 2020). "Importantly, recent work by our and other laboratories showed that IL-17B signaling dramatically alters the tumor microenvironment by promoting chemokine and cytokine secretion which foster tumor progression." (PMID 32373132, 2020). "IL-17B does not exert strong proinflammatory effects associated with IL-17A and is thought to contribute significantly to embryonic formation, tissue restoration, and tumor advancement." (PMID 40536951, 2026). "In addition, activated IL-17B/RB pathway in pancreatic stellate cells could also enhance PDAC tumor cell metabolism and proliferation." (PMID 39906741, 2024). "In our results, it is confirmed that the expression of IL-17A, IL-17B, IL-17C, IL-17D, IL-17E (IL-25), and IL-17F in tumor immune subtypes is statistically significant, especially in BRCA; there may be a potential microenvironmental regulation mechanism that remains to be investigated." (PMID 36159856, 2022). "Thus, IL-17B/IL-17RB signaling establishes a feedback loop between tumor cells and PSCs." (PMID 34771503, 2021). "In vivo studies further confirmed that FF suppressed tumor growth, reduced serum levels of ALT, AST, TNF-α, and IL-17B in mice, and modulated the expression of core target genes." (PMID 40630198, 2025). "IL-17B signaling can alter the tumor microenvironment (TME) by promoting chemokine and cytokine secretion, thereby facilitating tumor growth." (PMID 38478802, 2024). "Out of the six members of the IL17 family of cytokines, IL17A, IL17B, and IL17E have been found to aid in tumor growth, angiogenesis, metastasis, and chemoresistance." (PMID 37503343, 2023). "As for the result of the stage analysis, IL-17B had statistical significance in BRCA, and the low-expression group predicted tumor progression and poor patient prognosis." (PMID 36159856, 2022). "Depletion of IL-17B or IL-17RB by shRNA or treatment with anti-IL-17B or anti-IL-17RB antibodies reduces CFPAC-1 and BxPC3 pancreatic cell line colony formation, invasion, tumor growth, and metastasis in xenograft models." (PMID 32373132, 2020). "Although they were not able to detect IL-17E transcripts in the tumor cell lines, previous reports showed IL17B to be produced by malignant cells, inducing tumorigenesis in an autocrine manner." (PMID 37427128, 2023). "Various molecules, interleukin 17B (IL-17B) and transforming growth factor β (TGF-β), are involved in the recruitment of BM-MSCs into tumor microenvironment, and most of these molecules are also involved in the activation of CAFs following the differentiation of BM-MSCs into CAFs 2, 14, 17-19." (PMID 34093853, 2021). "Similarly, treatment with an IL-17B neutralizing antibody showed reduced CFPAC-1 and BxPC3 tumor cell xenograft growth and metastasis formation in vivo." (PMID 32373132, 2020). "In contrast, 7 out of 15 proteins including, IL17B (P = 0.0001), IP10 (P = 0.0135), LOX-1 (P < 0.0001), MIG (P < 0.0001), MIP-1d (P < 0.0001), SDC1 (P < 0.0001) and OPN (P < 0.0001) were significantly upregulated in tumour tissues compared to normal (AN and PN)." (PMID 34997107, 2022). "Our previous study revealed that GC tumor cells do not secrete IL-17B." (PMID 33649532, 2021).
tumor (continued). "In agreement with the absence of rIL-17B effect on MCF-7 and MDA-MB-468 cell proliferation in vitro, constitutive IL-17B expression in MCF7-h-IL17B and MDA-MB-468-h-IL-17B cells did not have any effect on their expansion in vitro and their tumor growth in vivo." (PMID 29371916, 2017).
infection (7 papers, 2012 to 2023). The state of being infected such as from the introduction of a foreign agent such as serum, vaccine, antigenic substance or organism. "Additionally, immediately following infection the AGMs exhibited increased expression of the gene encoding IL-17B, a T cell-derived cytokine with potential anti-inflammatory effects in the gut." (PMID 32119719, 2020). "An important gene for growth during stress, CHORDC1 associated with post-infection growth rate was identified as a positional candidate gene, as well as other immune related genes, including VAV2, IL12B, DUSP1, and IL17B." (PMID 32849779, 2020). "Plasma concentrations of pro-inflammatory IL-17 family members IL-17A, IL-17B, IL-17F and their common soluble receptor subunits, sIL-17RA and sIL-17RB, were quantified in AE patients with different states of disease and in infection-free controls." (PMID 22969818, 2012). "Individuals with polymorphisms in loci containing IL6, IL10, FCN2, RNASE3 and multiple Th17 pathway genes such as IL12B and IL17B had varying worm burden, indicating that these loci may play a role in determining infection intensity." (PMID 38033168, 2023). "But, in RIP3-/- mice or in MLKL-/- mice, IL-17B had little infection to the plasma IL-6 and TNF-α." (PMID 36046722, 2022). "Also in the course of allergic asthma, chemically-induced colitis or infection with C. rodentium, IL-17B exerts protective anti-inflammatory functions by interfering with IL-17E-induced IL-4 and IL-13 from type 2 Th cells and IL-6 from colon epithelial cells." (PMID 33244315, 2020). "We analyzed levels of pro-inflammatory IL-17 members (IL-17A, IL-17B and IL-17F) as well as their soluble common receptors (IL-17RA and IL-17RB) in clinically staged AE patients, that is, cured, stable, and progressive AE, and in infection-free controls." (PMID 22969818, 2012). "Although the role of IL-17B in pathogen infection is still not clear, it has been confirmed that IL-17B is protective and plays an important role in the regulation of mucosal inflammation." (PMID 32517220, 2020).
bacterial infection (2 papers, 2025 to 2026). "Previous studies have shown IL-17A/F, IL-17B, IL-17C, IL-17D and IL-17N could stimulate the expression of proinflammatory cytokines, chemokines and antimicrobial peptides in response to bacterial infection." (PMID 40149405, 2025).
inflammation (1 paper, 2020). Aberrant reaction of the microcirculation characterized by movement of fluid and leukocytes from the blood into extravascular tissues. "In rat models with indomethacin-induced intestinal inflammation, however, IL-17RB levels are increased, and intraperitoneal injection of IL-17B promotes the migration of neutrophils in normal mice, indicating that IL-17B has a pro-inflammatory function." (PMID 33132897, 2020).
IL17B also shares sentences with these, for which no sentence is quoted: schistosomiasis (2 papers); bronchitis (1); cerebrovascular disease (1); colorectal cancer (1); heart failure (1); Hepatic fibrosis (1); Hyperglycemia (1); lymphoma (1); prostate carcinoma (1); reproductive system diseases (1); urinary tract infection (1); urticaria (1).